GPR183 (G protein-coupled receptor 183)
Description:
G protein-coupled receptor expressed in lymphocytes that acts as a chemotactic receptor for B-cells, T-cells, splenic dendritic cells, monocytes/macrophages and astrocytes (By similarity). Receptor for oxysterol 7-alpha,25-dihydroxycholesterol (7-alpha,25-OHC) and other related oxysterols. Mediates cell positioning and movement of a number of cells by binding the 7-alpha,25-OHC ligand that forms a chemotactic gradient (By similarity). Binding of 7-alpha,25-OHC mediates the correct localization of B-cells during humoral immune responses (By similarity). Guides B-cell movement along the B-cell zone-T-cell zone boundary and later to interfollicular and outer follicular regions (By similarity). Its specific expression during B-cell maturation helps position B-cells appropriately for mounting T-dependent antibody responses (By similarity). Collaborates with CXCR5 to mediate B-cell migration; probably by forming a heterodimer with CXCR5 that affects the interaction between of CXCL13 and CXCR5. Also acts as a chemotactic receptor for some T-cells upon binding to 7-alpha,25-OHC ligand (By similarity). Promotes follicular helper T (Tfh) cells differentiation by positioning activated T-cells at the follicle-T-zone interface, promoting contact of newly activated CD4 T-cells with activated dendritic cells and exposing them to Tfh-cell-promoting inducible costimulator (ICOS) ligand (By similarity). Expression in splenic dendritic cells is required for their homeostasis, localization and ability to induce B- and T-cell responses: GPR183 acts as a chemotactic receptor in dendritic cells that mediates the accumulation of CD4(+) dendritic cells in bridging channels (By similarity). Regulates migration of astrocytes and is involved in communication between astrocytes and macrophages. Promotes osteoclast precursor migration to bone surfaces (By similarity). Signals constitutively through G(i)-alpha, but not G(s)-alpha or G(q)- alpha. Signals constitutively also via MAPK1/3 (ERK1/2) (By similarity).
Synonyms: EBI2; hEBI2
Tractability: Small molecule: a structure with a bound ligand is known; a high-quality ligand is known; it belongs to a druggable protein family. Antibody: UniProt places it where antibodies can reach, with high confidence; its Gene Ontology location is reachable by antibodies, with high confidence; UniProt predicts a signal peptide or a membrane-spanning region; the Human Protein Atlas places it where antibodies can reach. PROTAC: its protein half-life has been measured; a small molecule that binds it is known.
Target class: Family A G protein-coupled receptor; Membrane receptor
Chemical probes: ML401
Gene: Protein-coding gene on chromosome 13 (99,294,273 to 99,307,474, reverse strand). Ensembl gene ENSG00000169508.
Subcellular location: Cell membrane
Subcellular location (Human Protein Atlas): Plasma membrane; Nucleoplasm; Primary cilium; Primary cilium tip
Pathways (Reactome):
Signal Transduction: Class A/1 (Rhodopsin-like receptors); G alpha (i) signalling events
Gene Ontology:
Molecular function: G protein-coupled receptor activity; oxysterol binding; protein binding
Biological process: G protein-coupled receptor signaling pathway; leukocyte chemotaxis; positive regulation of B cell proliferation; positive regulation of ERK1 and ERK2 cascade; regulation of astrocyte chemotaxis; adaptive immune response; B cell activation involved in immune response; dendritic cell chemotaxis; dendritic cell homeostasis; humoral immune response; immune response; mature B cell differentiation involved in immune response; osteoclast differentiation; T cell chemotaxis; T follicular helper cell differentiation; cell chemotaxis
Cellular component: plasma membrane; membrane
Genetic constraint (gnomAD): Loss-of-function variants: 9 observed, 20.71 expected, observed/expected ratio (o/e) 0.43, 90% interval 0.26 to 0.76. The upper end of that interval is the gene's LOEUF score, 0.76, which puts it in group 3 of 6, group 1 being the genes least tolerant of losing a copy. Missense variants: 368 observed, 469.11 expected, observed/expected ratio (o/e) 0.78, 90% interval 0.72 to 0.86. Synonymous variants: 160 observed, 164.16 expected, observed/expected ratio (o/e) 0.97, 90% interval 0.86 to 1.11.
Homologues: Orthologues: chimpanzee GPR183 (99% identical), macaque GPR183 (99% identical), dog GPR183 (90% identical), guinea pig GPR183 (89% identical), pig GPR183 (89% identical), mouse Gpr183 (87% identical), rat Gpr183 (87% identical), rabbit GPR183 (78% identical), tropical clawed frog gpr183.2 (64% identical), zebrafish gpr183a (53% identical), zebrafish gpr183b (48% identical). Paralogues in human: RXFP3 (24% identical), GPR132 (21% identical), GPR174 (20% identical), P2RY11 (20% identical), GPR141 (15% identical), GPR151 (14% identical), GPR146 (12% identical).
Diseases named in the same sentence as GPR183 in open-access papers:
GPR183 is named in the same sentence as 75 diseases in open-access papers, as found by Europe PMC text mining. Sharing a sentence is not in itself a finding about the gene and the disease. The quoted sentences say what the papers report.
autoimmune disease (9 papers, 2013 to 2025). A disorder resulting from loss of function or tissue destruction of an organ or multiple organs, arising from humoral or cellular immune responses of the individual to their own tissue constituents. "The Epstein-Barr virus-induced gene 2 (EBI2, GPR183), one of the key immune system modulators, has been implicated in several chronic inflammatory and autoimmune diseases including rheumatoid arthritis, type 1 diabetes, inflammatory bowel disease and MS." (PMID 40656636, 2025). "GPR183 is highly regulated during cardiac inflammation, and may play key roles in pathogenesis of cardiovascular disease, inflammation and autoimmune diseases." (PMID 28407751, 2017).
colitis (8 papers, 2018 to 2025). Inflammation of the colon. "Localized oxysterol production by fibroblastic stromal cells provided an essential signal for colonic lymphoid tissue development, and inflammation-induced increased oxysterol production caused colitis through GPR183-mediated cell recruitment." (PMID 29343433, 2018). "Overall, our data demonstrate that inflammatory signals stimulate local oxysterol production and cause colitis through GPR183-dependent activation of ILC migration, myeloid cell recruitment, and tissue remodeling." (PMID 29343433, 2018). "Because of the increased expression in colonic T cells from patients with IBD, we tested the effect of GPR183 deficiency in the T cell transfer model of colitis, in which CD4+ CD45RBhigh (naïve) T cells, depleted of regulatory T cells, are adoptively transferred into Rag1-/- recipients." (PMID 36389671, 2022). "Based on the literature, including the effects of GPR183 deficiency on Group 3 innate lymphoid cells (ILC3) in the anti-CD40 induced colitis model, we investigated the effect of GPR183 deficiency on innate immune cells and other cell types in the T cell transfer model." (PMID 36389671, 2022). "Consequently, Gpr183-deficient mice were less susceptible to colitis in an innate model of intestinal inflammation." (PMID 29343433, 2018). "Despite its importance in regulating intestinal immune homeostasis, the overexpression of GPR183 is considered a pathological mechanism in colitis." (PMID 37720208, 2023). "On the other hand, in ILCs-related colitis models such as CD40 colitis, IL-10 colitis, T-bet (-/-) Rag2 (-/-) ulcerative colitis (TRUC), GPR183 is one of the pathogenic mechanisms." (PMID 37720208, 2023). "Although GPR183 primarily influences ILCs-related colitis models, it is considered a potential therapeutic target for the treatment of IBD." (PMID 37720208, 2023). "Our results are in contrast, however, to other findings suggesting GPR183 is relevant in some colitis models in which disease is initiated by stimulating the innate rather than the adaptive immune system." (PMID 36389671, 2022). "We found that Gpr183 mRNA was slightly but significantly elevated in the colons of mice in the T cell transfer model of colitis, which is highly dependent on adaptive immunity." (PMID 36389671, 2022). "Based on the GWAS and gene expression studies, we analyzed the role of GPR183 in the T cell transfer model of colitis." (PMID 36389671, 2022). "However, in the DSS colitis model, GPR183 knockout resulted in a reduction of colonic lymphoid structures but did not alleviate the severity of acute or chronic inflammation induced by DSS." (PMID 37720208, 2023). "Furthermore, we found that the expression of GPR183 mRNA was increased in patients resistant to TNF blockade therapies compared to responders, and Gpr183 expression was increased in colon tissue in the T cell transfer model of colitis." (PMID 36389671, 2022). "Furthermore, histopathologic scoring of the colon sections revealed that the colitis severity was similar when Gpr183-/- or control T cells were injected into Rag1-/- recipients." (PMID 36389671, 2022). "Furthermore, 7α,25-OHC was increased by inflammatory signals, and GPR183 controlled inflammatory cell recruitment during colitis." (PMID 29343433, 2018). "Furthermore, CD40-treated Gpr183−/−Rag1−/− mice developed only mild colitis with an inflammation score similar to that of PBS-treated Gpr183+/+Rag1−/− mice." (PMID 29343433, 2018). "Therefore, it is speculated that the destruction of the epithelial barrier and innate immune response are the main factors involved in the pathogenesis of the DSS colitis model, while GPR183 plays a minor role." (PMID 37720208, 2023). "In colitis induced by exposure to a low dose of DSS, Il10-/-Gpr183-/- animals had less severe inflammation compared to Il10-/- controls." (PMID 36389671, 2022). "We also studied the roles of GPR18 and GPR183 in the T cell transfer model and GPR18 in the DSS model of colitis." (PMID 36389671, 2022).
colitis (continued). "In a mouse model of colitis initiated by innate immune activation with anti-CD40 mAb, GPR183 was important for the localization of ILC and for inducing inflammation." (PMID 36389671, 2022). "In DSS induced colitis, however, which does not depend on T cells, GPR183 did not contribute to pathogenesis unless the mice were on the Il10-/- gene background." (PMID 36389671, 2022). "Our results agree with those from a study showing Gpr183-/- mice were not different from wild type controls in a DSS model of colitis." (PMID 36389671, 2022). "In the T cell transfer model, GPR183 expression on donor T cells, as well as on other cell types in the Rag-/- recipients, was not essential for severe colitis induction." (PMID 36389671, 2022). "Like GPR183, GPR18 transcripts increased in microarray expression data from colon biopsies of UC and Crohn’s disease patients versus healthy controls and in colon tissue from mouse models of colitis." (PMID 36389671, 2022). "Also, we have not excluded the possibility that deletion of Gpr183 on both the donor T cells and the Rag1-/- hosts would have had an effect on colitis induction." (PMID 36389671, 2022). "This group also detected increased Gpr183, Ch25h and Cyp7b1 expression in the acute and chronic DSS colitis models, but they did not observe an effect of Gpr183 or Ch25h gene deficiency on inflammation severity." (PMID 36389671, 2022). "Therefore, although Gpr18 expression was increased in the colon in colitis patients and in two mouse models of colitis, expression of GPR18, like as for GPR183, does not play a role in regulating disease severity." (PMID 36389671, 2022).
inflammatory bowel disease (8 papers, 2018 to 2025). A spectrum of small and large bowel inflammatory diseases of unknown etiology. "The G protein–coupled receptor GPR183 regulates immune cell migration and intestinal immune response and has been associated with tuberculosis, type 1 diabetes, and inflammatory bowel diseases." (PMID 39545055, 2024). "The GPR183 locus is a risk locus for inflammatory bowel diseases (IBD), suggesting a role for oxysterols in IBDs." (PMID 36293093, 2022). "Antagonistic approaches have been discussed for GPR183 in inflammatory bowel diseases, rheumatoid arthritis, and in viral infections, and several GPR183 targeting compounds have already been developed." (PMID 39545055, 2024). "This seemed particularly relevant given that hyperplastic lymphoid aggregates occur in human inflammatory bowel disease (IBD), and polymorphisms in Gpr183 have been associated with IBD." (PMID 29343433, 2018). "This suggests a role of Gpr183 in the interplay between intestinally located and circulating immune cells, accordingly, an antagonistic approach has already been raised with evidence in inflammatory bowel diseases and rheumatoid arthritis to impair autoimmune responses within the intestines." (PMID 39545055, 2024). "While this study was underway, several groups focused on GPR183 in IBD, and its expression was found to be increased in inflammatory bowel disease patients." (PMID 36389671, 2022).
type 1 diabetes (7 papers, 2012 to 2025). "MEG3 and GPR183 were shown to be involved in the development of type 1 diabetes." (PMID 23145134, 2012).
lupus (6 papers, 2015 to 2026). "Here, we show that in systemic lupus erythematosus, GPR183-expressing B cells are reduced in both humans and mice with established disease, irrespective of sex." (PMID 41816282, 2026). "Treatment with GPR183 antagonist NIBR189 significantly suppressed experimental lupus severity, as measured by lower proteinuria score (3.2 in NIBR189-treated mice vs. 1.1 in control lupus mice, p=0.0006)." (PMID 36096831, 2022).
Burkitt lymphoma (5 papers, 2015 to 2023). A rare form of malignant mature B-cell non-Hodgkin lymphoma. "G protein-coupled receptor 183 (GPR183) was discovered in 1993 as an Epstein–Barr virus-induced orphan receptor in Burkitt lymphoma cell lines, which is important for rapid and efficient B-cell activation." (PMID 38046263, 2023). "GPR183 was discovered in 1993 as an Epstein-Barr virus-induced orphan receptor in Burkitt lymphoma cell lines, hence its previous name is Epstein-Barr virus-induced G-protein coupled receptor 2 (EBI2)." (PMID 36389671, 2022). "EBI2, aka GPR183, is a G-couple receptor originally identified in 1993 as one of main genes induced in Burkitt’s lymphoma cell line BL41 by Epstein–Barr virus (EBV) infection." (PMID 25852561, 2015).
glioblastoma multiforme (5 papers, 2019 to 2025). "In glioblastoma multiforme, GPR183 contributed to chemotactic migration of THP-1 cells toward tumor." (PMID 32195260, 2020). "GPR183 is a sensor for oxysterols, which are released by glioblastoma cells and play a role in recruitment of immune cells." (PMID 32299465, 2020).
Obesity (4 papers, 2015 to 2024). Accumulation of substantial excess body fat. "The same study also described a correlation between body mass index and 25-OHC in males with obesity, which underscores sexual dimorphism in oxysterol interactions and indicates a pivotal role of the Gpr183-oxysterol axis in weight regulation from an early age and during weight increase." (PMID 39545055, 2024). "We proposed the possibility that upregulated GPR183 may contribute to recruiting immune cells in AT under obesity conditions due to its crucial role in immune modulation." (PMID 35894174, 2022). "GPR183 is a newly identified gene that dramatically increased in AT of obese patients whose role in obesity is unknown." (PMID 35894174, 2022). "However, the function of other DEGs like GPR183 and PGAM2 in the progress of obesity is lacking and remains to be explored." (PMID 35894174, 2022).
viral infection (4 papers, 2014 to 2025). "GPR183 has also been shown to play diverse roles in bacterial and viral infections with a clear link to metabolism." (PMID 39545055, 2024).
Autoimmunity (3 papers, 2013 to 2026). The occurrence of an immune reaction against the organism's own cells or tissues. "Sensing oxidized cholesterol (oxysterol) ligands by GPR183-expressing B cells spatially regulates B cell activation within secondary lymphoid tissues, which, when dysregulated, could contribute to B cell-driven autoimmunity." (PMID 41816282, 2026).
experimental autoimmune encephalomyelitis (3 papers, 2022 to 2025). An autoimmune demyelinating disease of the central nervous system that is produced experimentally in animals by the injection of homogenized brain or spinal cord in Freund's adjuvant. "GPR183 had not been implicated in IBD studies at the time this work began, but it had been found to influence B lymphocyte localization during the germinal center response, and was shown to mediate migration of T cells into the inflamed CNS in an experimental autoimmune encephalomyelitis model." (PMID 36389671, 2022).
liver fibrosis (3 papers, 2019 to 2024). "The same trend was observed in male Gpr183–/– compared to male WT with significantly lower levels of pro-inflammatory marker Il1β, liver fibrosis markers α-SMA, Col1a1, and Mcp1, and macrophage markers Adgre1 and Cd14." (PMID 39545055, 2024). "Female Gpr183–/– mice showed a trend of overall lower levels with significantly lower levels of liver fibrosis markers Col1a1 and Mcp1 compared to WT females, a pattern opposite of that observed in VAT macrophage infiltration." (PMID 39545055, 2024).
breast carcinoma (2 papers, 2020 to 2026). "In vivo validation using immunohistochemistry on clinical samples from 10 breast cancer patients with ovarian metastases confirmed that GPR183, BHLHE41, and CD83 were highly expressed in tumor tissues, while SLC25A37 and SELL were highly expressed in adjacent normal tissues." (PMID 42101520, 2026). "Overall, CCL19, CCL21, GPR183, P2RY13, and PENK were potential protective factors in breast cancer." (PMID 32195260, 2020).
COVID-19 (2 papers, 2021 to 2024). A disease caused by infection with severe acute respiratory syndrome coronavirus 2. "Additionally, there are 1155 and 22 ligand candidates for CCR1 and GPR183, surface targets enriched in severe COVID-19, in BindingDB, respectively." (PMID 34239034, 2021).
lymphoma (2 papers, 2019 to 2024). A malignant (clonal) proliferation of B- lymphocytes or T- lymphocytes which involves the lymph nodes, bone marrow and/or extranodal sites. "Epstein-Barr Virus (EBV) induced gene 2 (EBI2) is a G-Protein Coupled Receptor (GPCR), also known as GPR183, which was originally identified as the main induced gene in Burkitt's Lymphoma cells upon infection with EBV." (PMID 30918887, 2019).
tuberculosis (2 papers, 2020 to 2024). A chronic, recurrent infection caused by the bacterium Mycobacterium tuberculosis. "For example, whole-blood GPR183 expression is downregulated in people with tuberculosis (TB) and additionally type 2 diabetes compared to people with TB alone." (PMID 39545055, 2024). "We found that expression of the oxysterol-receptor GPR183 was reduced in blood from patients with tuberculosis (TB) and type 2 diabetes (T2D) compared to TB patients without T2D and was associated with TB disease severity on chest x-ray." (PMID 33240287, 2020).
type 2 diabetes (2 papers, 2022 to 2024). "The oxysterol receptor GPR183 was found to be a negative regulator of type I IFN in human monocytes where gene expression of IRF1, IRF5 and IRF7 is upregulated in type 2 diabetic patients who are TB-positive, thus corresponding to the down regulation of GPR183." (PMID 36286068, 2022).
asthma (1 paper, 2025). "The potential importance of GPR183 has recently been suggested by a clinical study in asthma patients, which found that the therapeutic efficacy of anti-IL-5 treatment correlated with reduced GPR183 expression on type 2 lymphocytes." (PMID 40766699, 2025). "GPR183 levels in type 2 lymphocytes were reported to be strongly correlated with asthma outcomes following anti-IL-5 antibody treatment, highlighting the potential importance of GPR183 in regulating pulmonary type 2 immunity." (PMID 40766699, 2025).